MINDY3 (MINDY lysine 48 deubiquitinase 3)
Description:
Hydrolase that can remove 'Lys-48'-linked conjugated ubiquitin from proteins.
Synonyms: C10orf97; CARP; DERP5; FAM188A; MSTP126; My042; FLJ13397; MST126
Tractability: PROTAC: ubiquitination databases record sites on it.
Gene: Protein-coding gene on chromosome 10 (15,778,170 to 15,860,528, reverse strand). Ensembl gene ENSG00000148481.
Subcellular location: Nucleus
Subcellular location (Human Protein Atlas): Nuclear membrane; Nucleoplasm; Cytosol; Microtubules; Primary cilium; Primary cilium tip
Gene Ontology:
Molecular function: cysteine-type deubiquitinase activity; K48-linked deubiquitinase activity; protein binding
Biological process: protein K48-linked deubiquitination
Cellular component: nuclear membrane; nucleoplasm; nucleus
Genetic constraint (gnomAD): Loss-of-function variants: 12 observed, 26.47 expected, observed/expected ratio (o/e) 0.45, 90% interval 0.29 to 0.73. The upper end of that interval is the gene's LOEUF score, 0.73, which puts it in group 3 of 6, group 1 being the genes least tolerant of losing a copy. Missense variants: 266 observed, 279.94 expected, observed/expected ratio (o/e) 0.95, 90% interval 0.86 to 1.05. Synonymous variants: 103 observed, 96.82 expected, observed/expected ratio (o/e) 1.06, 90% interval 0.91 to 1.25.
Homologues: Orthologues: macaque MINDY3 (100% identical), chimpanzee MINDY3 (99% identical), rabbit MINDY3 (99% identical), dog MINDY3 (98% identical), pig MINDY3 (98% identical), guinea pig MINDY3 (97% identical), mouse Mindy3 (96% identical), rat Mindy3 (95% identical), tropical clawed frog mindy3 (76% identical), zebrafish mindy3 (75% identical), Drosophila melanogaster CG7332 (47% identical). Paralogues in human: MINDY4 (26% identical), MINDY4B (20% identical).
Diseases named in the same sentence as MINDY3 in open-access papers:
MINDY3 is named in the same sentence as 3 diseases in open-access papers, as found by Europe PMC text mining. Sharing a sentence is not in itself a finding about the gene and the disease. The quoted sentences say what the papers report.
retinal degeneration (1 paper, 2025). Degeneration of the retina. "Potential interacting molecules involved in retinal degeneration or visual cycle, including MINDY3, EPG5, miR‐548b‐3p, OTX2, miR‐519d, LRAT, and NR2E3, were selected based on the STRING and miRDB (MicroRNA Target Prediction Database) databases." (PMID 40956390, 2025).
cancer (1 paper, 2023). A tumor composed of atypical neoplastic, often pleomorphic cells that invade other tissues. "For instance, we use it to identify novel cancer-related genes, i.e. PRDM11, C9orf72, MINDY3, and H4C6, that could have an important role in the studied cancer types." (PMID 37084262, 2023).
MINDY3 also shares sentences with these, for which no sentence is quoted: melanoma (1 paper).